SLC2A8 (solute carrier family 2 member 8)
Description:
Insulin-regulated facilitative hexose transporter that mediates the transport of glucose and fructose (By similarity). Facilitates hepatic influx of dietary trehalose, which in turn inhibits glucose and fructose influx triggering a starvation signal and hepatic autophagy through activation of AMPK and ULK1. Also able to mediate the transport of dehydroascorbate.
Synonyms: GLUT8; GLUTX1
Tractability: Antibody: its Gene Ontology location is reachable by antibodies, with high confidence; UniProt places it where antibodies can reach, with medium confidence; UniProt predicts a signal peptide or a membrane-spanning region. PROTAC: ubiquitination databases record sites on it; its protein half-life has been measured; a small molecule that binds it is known.
Target class: SLC superfamily of solute carriers; Electrochemical transporter; SLC02 family of hexose and sugar alcohol transporters; Transporter
Gene: Protein-coding gene on chromosome 9 (127,397,138 to 127,408,424, forward strand). Ensembl gene ENSG00000136856.
Subcellular location: Cell membrane; Cytoplasmic vesicle membrane
Subcellular location (Human Protein Atlas): Vesicles
Pathways (Reactome):
Vesicle-mediated transport: Cargo recognition for clathrin-mediated endocytosis; Clathrin-mediated endocytosis
Transport of small molecules: Cellular hexose transport
Gene Ontology:
Molecular function: D-glucose transmembrane transporter activity; dehydroascorbic acid transmembrane transporter activity; fructose transmembrane transporter activity; D-glucose binding; transmembrane transporter activity
Biological process: carbohydrate metabolic process; D-glucose transmembrane transport; dehydroascorbic acid transport; fructose transmembrane transport; hexose transmembrane transport; male meiosis I; transmembrane transport
Cellular component: lysosomal membrane; clathrin-coated endocytic vesicle membrane; cytoplasmic vesicle membrane; plasma membrane; membrane; synaptic vesicle
Genetic constraint (gnomAD): Loss-of-function variants: 53 observed, 42 expected, observed/expected ratio (o/e) 1.26, 90% interval 1.01 to 1.59. The upper end of that interval is the gene's LOEUF score, 1.59, which puts it in group 6 of 6, group 1 being the genes least tolerant of losing a copy. Missense variants: 688 observed, 577.33 expected, observed/expected ratio (o/e) 1.19, 90% interval 1.12 to 1.27. Synonymous variants: 299 observed, 253.63 expected, observed/expected ratio (o/e) 1.18, 90% interval 1.07 to 1.3.
Homologues: Orthologues: chimpanzee SLC2A8 (99% identical), rabbit SLC2A8 (90% identical), dog SLC2A8 (89% identical), macaque SLC2A8 (89% identical), pig SLC2A8 (88% identical), mouse Slc2a8 (86% identical), rat Slc2a8 (86% identical), guinea pig SLC2A8 (83% identical), tropical clawed frog slc2a8 (61% identical), zebrafish slc2a8 (58% identical), Drosophila melanogaster nebu (36% identical), Drosophila melanogaster Tret1-1 (35% identical), and 32 more. Paralogues in human: SLC2A6 (43% identical), SLC2A12 (30% identical), SLC2A13 (30% identical), SLC2A4 (28% identical), SLC2A3 (28% identical), SLC2A10 (27% identical), SLC2A14 (27% identical), SLC2A1 (26% identical), SLC2A2 (26% identical), SLC2A5 (26% identical), SLC2A11 (25% identical), SLC2A7 (24% identical), and 1 more.
Diseases named in the same sentence as SLC2A8 in open-access papers:
SLC2A8 is named in the same sentence as 17 diseases in open-access papers, as found by Europe PMC text mining. Sharing a sentence is not in itself a finding about the gene and the disease. The quoted sentences say what the papers report.
neuroblastoma (2 papers, 2017 to 2018). Neuroblastoma (NB) is the most common solid, extracranial childhood tumor. "However, trehalose-induced LC3-II accumulation in N2A neuroblastoma cells was not SLC2A8-dependent, because SLC2A8 is not localized in the plasma membrane in neuronal cells." (PMID 29907758, 2018).
placental insufficiency (2 papers, 2019 to 2024). Failure of the placenta to deliver an adequate supply of nutrients and oxygen to the fetus. "As the mammalian placenta utilizes the majority of oxygen and glucose taken up from the maternal circulation, for oxidative processes, our results suggest that SLC2A8 deficiency would likely impair intracellular glucose transport and oxidation, resulting in functional placental insufficiency." (PMID 38474355, 2024). "Therefore, it may be possible that dysregulation of SLC2A8 expression and glucose uptake leads to disturbed mitochondria function, resulting in pregnancy disorders associated with placental insufficiency and glucose supply below demand." (PMID 38474355, 2024). "Slc2a8/Glut8 has been detected in sheep, with decreased expression in a placental insufficiency model, and increased expression in placentae of cortisol-infused ewes, a model of stress during pregnancy." (PMID 31774824, 2019). "These authors conclude that the decreased placental SLC2A8 concentration observed in an ovine model of placental insufficiency and IUGR may contribute to the reduction in placental glucose transport." (PMID 38474355, 2024). "Since the placenta oxidizes the majority of the glucose it takes up to support its own metabolic needs, impairment of SLC2A8 function could set the stage for functional placental insufficiency." (PMID 38474355, 2024).
breast carcinoma (1 paper, 2021). "Additionally, there is a certain interaction between abnormal mRNA expression of SLC2A6, SLC2A8, SLC2A9 and prognosis in breast cancer (HR: 1.13 [1.06–1.62];p = 0.013, HR: 1.28 [1.03–1.59];p = 0.027 and HR: 0.78 [0.61–0.99];p = 0.043, respectively)." (PMID 34488531, 2021).
dementia (1 paper, 2022). Loss of intellectual abilities interfering with an individual's social and occupational functions. "These loci are associated with several dementia-related genes, including PON1, AP2A2, MAGI2, POT1, ITGAX, PACSIN1, SLC2A8, and EIF4E." (PMID 35299244, 2022).
epilepsy (1 paper, 2023). A brain disorder characterized by episodes of abnormally increased neuronal discharge resulting in transient episodes of sensory or motor neurological dysfunction, or psychic dysfunction. "For instance, the human SLC2A8 gene is orthologous to 16 of these 224 epilepsy-related Drosophila genes." (PMID 36873106, 2023).
Infertility (1 paper, 2008). "The effects on ΔΨm and ATP levels in Slc2a8−/− males did not lead to infertility; Slc2a8 knockout sperm were able to fertilize Slc2a8 wild-type oocytes." (PMID 18428038, 2008).
Insulin resistance (1 paper, 2020). Increased resistance towards insulin, that is, diminished effectiveness of insulin in reducing blood glucose levels. "Whereas gene expression of Slc2a8 is reduced in mouse models of autoimmune type 1 diabetes, GLUT8 expression increases in insulin resistance and type 2 diabetes, suggesting that the expression is regulated by insulin." (PMID 32591906, 2020).
myeloma (1 paper, 2022). "Of the 13 members of the Slc2 family in mice, primary plasma cells and/or myeloma cells expressed SLC2A3, SLC2A6, and SLC2A8 as candidate glucose transporters in addition to SLC2A1." (PMID 36001583, 2022).
Obesity (1 paper, 2024). Accumulation of substantial excess body fat. "Thus, SLC2A8 methylation could play a role in the prevention of the obesity-related phenotype induced by pregestational obesity." (PMID 38397903, 2024).
tumor (3 papers, 2021 to 2022). "The combination treatment transcriptionally upregulated tumor expression of SLC2A8 and FoxO6, important genes for glucose uptake, metabolism and redox balance." (PMID 34578801, 2021). "The most likely explanation for the tumor essentiality of transporter protein genes SLC16A3, SLC2A1, and SLC2A8 is that tumor cells have an increased demand for nutrients and this demand is met by enhanced cellular entry of nutrients through upregulation of specific transporters." (PMID 33427197, 2021). "In harmony with this conclusion NOVA1, SLC16A3, SLC2A8, and TP73 were assigned to the essential category by De Kegel and Ryan, 2019 in less than 10% of the 558 tumor cell lines tested." (PMID 33427197, 2021).
SLC2A8 also shares sentences with these, for which no sentence is quoted: cancer (2 papers); diabetes (1); Hepatic steatosis (1); Hyperinsulinemia (1); metabolic disease (1); pregnancy disorder (1); type 2 diabetes (1).